EPCAM (epithelial cell adhesion molecule)
Diseases named in the same sentence as EPCAM in open-access papers (continued):
Sharing a sentence is not in itself a finding about the gene and the disease.
cholangiocarcinoma (21 papers, 2009 to 2026). A carcinoma that arises from the intrahepatic biliary tree (intrahepatic cholangiocarcinoma) or from the junction, or adjacent to the junction, of the right and left hepatic ducts (hilar cholangiocarcinoma). "Epithelial cell adhesion molecule (EpCAM) is a tumor-associated antigen that is aberrantly overexpressed on many epithelial-derived cancers, including on cholangiocarcinoma (CCA) cells." (PMID 39513807, 2024). "These aptamers exhibit high binding and affinity, as well as specificity for EpCAM expressed on cholangiocarcinoma (CCA) cells." (PMID 40807559, 2025). "The applicability of GenoCTC to different cell surface biomarkers was also validated in a cholangiocarcinoma patient using anti-EPCAM, anti-vimentin, or anti-tyrosine protein kinase MET (c-MET) antibodies." (PMID 32486306, 2020). "We confirmed that all of the cholangiocarcinoma derived lines expressed the epithelial markers EpCAM, CK19 and epithelial membrane antigen NCAM and GCTM-5." (PMID 25701818, 2015). "Similarly, tumor cells over-expressing EpCAM have been applied to capture them from liquid biopsy by using multiple techniques, and EpCAM has also been found over-expressed in cholangiocarcinoma and gallbladder cancer." (PMID 28652576, 2017). "Markers, such as CD133, CD24, EpCAM and CD44 have been used to isolate cholangiocarcinoma stem cells." (PMID 26097877, 2015). "The strongest EPCAM expression was seen in adenocarcinomas from the GI tract, i.e., small bowel, colon, pancreas, and cholangiocarcinomas but, also, in intestinal and diffuse gastric carcinomas, although gastric foveolar epithelium was EPCAM-negative." (PMID 33003511, 2020). "Here, we enumerated and analyzed CTCs from a cholangiocarcinoma patient using the epithelial marker EPCAM and the non-epithelial markers vimentin and MET." (PMID 32486306, 2020). "Here we also found that glucose depletion in cholangiocarcinoma organoids induced an increase in their expression of stem cell markers, including LGR5, CD44, EpCAM, NANOG and OCT4 and more pronounced stem cell phenotypic characteristics such as resistance to gemcitabine." (PMID 31835877, 2019). "For further marker validation, we compared the detection rate for HCC CTCs using three HCC markers verses EpCAM in a pilot cohort of 12 HCC patients and 4 cholangiocarcinoma (CCA) patients." (PMID 31819089, 2019). "EpCAM expression levels are correlated with negative prognosis and treatment response in cholangiocarcinoma (CCA), breast, bladder, and ovarian cancers, amongst others." (PMID 39513807, 2024). "They purified AnnexinV+,EpCAM+ CD147+ EVs from patients with HCC and Cholangiocarcinoma (CCA) (n = 127), with liver cirrhosis (n = 54), and negative controls (n = 202)." (PMID 34205183, 2021).
glioblastoma (21 papers, 2011 to 2025). The most malignant astrocytic tumor (WHO grade IV). "Conventional CTC location stages regularly depend on epithelial cell grip atom (EpCAM)-based enhancement, which is imperfect for glioblastoma cells that ordinarily need EpCAM expression." (PMID 41311621, 2025). "A primary priority is the systematic validation of marker panels suitable for EpCAM-negative glioblastoma CTCs, including mesenchymal and stem cell-associated markers, across independent cohorts and laboratories." (PMID 41514523, 2025). "Therefore, targeting ERBB receptor family members like EGFR, ERBB2 or ERBB3 alone or in combination with other epithelial markers such as EpCAM, will provide opportunities to detect and isolate CTCs that represent primary tumors of ovarian and glioblastoma." (PMID 29321816, 2017). "While the positive selection for EpCAM is useful for most epithelial cancers, it is not suitable for glioblastoma because neural tumors usually lack EpCAM expression, but it has potential for glioblastoma, when the right markers will be applied; Specific CD44 variants may be an option." (PMID 41514523, 2025). "Unlike epithelial cancers, where EpCAM provides a broadly applicable target, glioblastoma lacks a single, well-validated surface marker that combines sensitivity and specificity." (PMID 41514523, 2025). "The CellSearch® System, validated by the FDA, is a robust method but has limited applicability in glioblastoma because it primarily targets epithelial markers, such as EpCAM, which are often absent in tumors of the central nervous system (CNS), including GBM." (PMID 40427551, 2025). "Glioblastoma CTCs are typically EpCAM-negative, so alternative methods like iChip, ScreenCellTM, and pluriBeadTM are under investigation." (PMID 41514523, 2025). "Furthermore, glioblastoma stem cell (GSCs, X01) membrane CM (X01) had CD44, one of stem markers, as well as EpCAM, both of which were helpful to target homotypic cells." (PMID 37507371, 2023). "Conversely, a significant reduction in EpCAM expression was noted in colon adenocarcinoma (COAD), glioblastoma multiforme (GBM), as well as in liver hepatocellular carcinoma (LIHC) and renal cancer." (PMID 38187284, 2024). "Initially, this was confirmed using a glioblastoma xenograft that does not express EpCAM." (PMID 23460885, 2013).
nasopharyngeal carcinoma (20 papers, 2013 to 2024). A carcinoma arising from the nasopharyngeal epithelium. "It revealed that nasopharyngeal carcinoma cell lines overexpressing EpCAM had a significant increase in the level of crucial molecules of this pathway, such as mTOR and activated Akt." (PMID 35986321, 2022). "In this study, the prognostic impact of histopathologic features including EpCAM for nasopharyngeal cancer (NPC) patients was investigated." (PMID 31822892, 2020). "Also, it confirms that activation of the Akt/mTOR signaling pathway is necessary for EMT, resulted from EpCAM overexpression in nasopharyngeal carcinoma cells." (PMID 35986321, 2022). "In nasopharyngeal carcinoma role of EpCAM in metastasis is evaluated in vivo." (PMID 33490064, 2020). "It is also reported that EpCAM regulates stemness in nasopharyngeal carcinoma." (PMID 33490064, 2020). "These suggest the importance of EpCAM in nasopharyngeal carcinoma." (PMID 28959019, 2017). "EpCAM is an unfavorable prognostic factor, and its overexpression can promote metastasis in nasopharyngeal carcinoma (NPC)." (PMID 38187284, 2024). "Consistently, EpCAM has been shown to promote a more aggressive and drug-resistant phenotype through the activation of the AKT pathway in ovarian and nasopharyngeal cancers." (PMID 38791091, 2024). "Another clinical trial directed at EpCAM is NCT02915445, in which the safety of EpCAM CAR-T cells was determined in 30 patients with nasopharyngeal carcinoma or BC expressing high levels of EpCAM." (PMID 36899854, 2023). "In nasopharyngeal carcinoma (NPC), enhanced EpCAM expression downregulated PTEN while promoting the phosphorylation of AKT, mTOR, p70S6K and 4EBP1." (PMID 36369033, 2022). "Here we showed high expression of EpCAM, CD56, CD58 and CD90 by flow cytometry in two pediatric carcinomas (an adrenal carcinoma and a nasopharyngeal carcinoma)." (PMID 23472067, 2013). "More recently, in nasopharynx carcinoma, the mesenchymal markers N-cadherin, Vimentin, β-catenin and the EMTTF Slug were significantly upregulated, whereas the epithelial markers α-catenin and E-cadherin were decreased in the EpCAM expressing cells." (PMID 31225512, 2019). "However, CAR-T cells targeting the epithelial cell adhesion molecule (EpCAM), natural killer group 2 member D ligand (NKG2DL) and latent membrane protein (LMP1) remain in clinical trials to verify their safety and efficacy for the treatment of nasopharyngeal carcinoma." (PMID 36983174, 2023).
sarcoma (19 papers, 2015 to 2025). A usually aggressive malignant neoplasm of the soft tissue or bone. "Accordingly, a strong variance in EpCAM expression has been documented between histotypes in pediatric sarcomas and the association with patient outcome." (PMID 34063272, 2021). "Although EpCAM is commonly overexpressed in epithelial tumors, its expression in sarcomas is variable, yet it can still aid in detecting circulating sarcoma cells." (PMID 39456239, 2024). "In a study that compared CTC detection rates of EpCAM and CSV as capture antibodies for sarcoma patient samples, Kang and collaborators reported a 0% rate for EpCAM, but a 90% rate for CSV29." (PMID 38811642, 2024). "A dynamic expression of EpCAM during tumor evolution has been observed in diverse sarcoma subtypes, with a correlation between high EpCAM expression and significantly poorer patient’s OS and adverse outcome." (PMID 34063272, 2021). "RMS cells express the lowest levels of EpCAM and E-cadherin among all sarcoma histotypes due to PAX3-FOXO1 transcription factor, which antagonizes wild-type Pax3-induced cell aggregation and epithelioid changes." (PMID 34063272, 2021). "The discovery of EpCAM mRNA expression in different sarcoma cell lines and in a small cohort of metastatic sarcoma patients supports further investigations on these rare tumors to deepen the importance of CTC isolation." (PMID 26167450, 2015). "The numbers of CTC-positive in patients with sarcoma and total CTCs in pediatric sarcomas are similar to data previously reported at diagnosis in carcinomas, with progressive disease and poor outcome in patients with the highest EpCAM levels." (PMID 34063272, 2021). "More recently, EpCAM-positive circulating cells were detected in soft tissue sarcoma patients and a genomic meta-analysis of gene expression profiles demonstrated that EpCAM mRNA is expressed in different sarcoma cell lines." (PMID 26167450, 2015). "Vice versa, co-stimulation through EpCAM or HER-2 significantly enhanced FAP-mediated tumor cell lysis, suggesting that T cells engaged carcinoma and sarcoma cells concomitantly." (PMID 34484225, 2021). "Thus EpCAM-positive tumor cells might exert a role in metastasis in sarcoma." (PMID 34063272, 2021). "A total of 91 recruited cancer patients had performed CTC detection by EpCAM and CSV antibodies at same time, including 20 LC, 8 CRC, 20 PDAC, 10 GC, 10 BCa, 4 HCC, 8 CC, 4 EC, 4 OC and 3 sarcoma." (PMID 33717672, 2021). "EpCAM is not expressed on tumors of mesodermal and ectodermal origin, such as neurogenic tumors, sarcomas, melanomas, or lymphomas." (PMID 33717672, 2021). "These methods exploit differences between biological and/or physical properties of CTCs and normal blood cells rather than use antibodies to the epithelial marker EpCAM, which is not expressed by cells derived from sarcoma tumors." (PMID 28403214, 2017). "Also, the presence of epithelial cell adhesion molecule (EpCAM)-positive CTC in sarcoma has been weakly correlated with poor outcome and disease progression, thus proving the existence of both epithelial and mesenchymal CTC in sarcoma." (PMID 34063272, 2021). "Although it is not clear whether EpCAM expression might be originally present on tumor sarcoma cells or acquired during the mesenchymal-epithelial transition, the discovery of EpCAM on circulating sarcoma cells opens a new scenario in CTC detection in patients affected by a rare mesenchymal tumor." (PMID 26167450, 2015). "In contrast to neuroblastic tumors, soft tissue tumors and other extraosseous sarcomas—n = 20 (18%), with 19/20 infiltrated by MFC—had a common CD56++ CD271++ CD81++ phenotype in the absence of CD45, CD34, and EpCAM expression, with three distinct (heterogeneous) phenotypic profiles." (PMID 34638431, 2021).
thyroid cancer (19 papers, 2010 to 2026). "Although several studies demonstrated the association of aggressiveness of thyroid cancer and localization of EpCAM, the involvement of EpCAM in carcinoma-specific complexes with variant isoforms of CD44 and claudin-7 has not been studied in thyroid cancer." (PMID 24727741, 2014). "In our study, flow cytometry analysis revealed an inverse association between the expression of EpCAM and CD44s was observed in thyroid cancer cell lines." (PMID 24727741, 2014). "While in some cancer types, including renal cell and thyroid cancer, EpCAM expression is associated with an improved survival, in other tumors high intratumoral EpCAM expression was identified as a poor prognostic factor." (PMID 23830302, 2013). "Thus, a positive association between the expression of ALDH1 and EpCAM was observed in the thyroid cancer cell lines." (PMID 24727741, 2014). "Of late, nuclear accumulation of the intracellular domain of EpCAM and a reciprocal loss of the membranous extracellular domain of EpCAM was demonstrated to predict poor prognosis of patients with thyroid cancers and is associated with reduced overall survival." (PMID 24727741, 2014). "In this study, we investigated the function of EpCAM in thyroid cancer cell lines of varying differentiation status." (PMID 41785279, 2026). "Further studies are warranted to elucidate the mechanisms linking EpCAM to anaplastic transformation and to explore the therapeutic efficacy of EpCAM-targeting strategies in aggressive thyroid cancers." (PMID 41785279, 2026). "EpCAM expression was significantly elevated in ATC cell lines compared with differentiated thyroid cancer (DTC) lines." (PMID 41785279, 2026). "Our results provide new insights into the role of EpCAM in thyroid cancer biology and highlight its potential as a therapeutic target in ATC." (PMID 41785279, 2026). "This analysis revealed that seven of the novel identified variants were located in genes previously associated with thyroid cancer: MSH6, FOXM1, EPCAM, HOOK3, BMP1, TG and NTRK1." (PMID 37175550, 2023). "This is the first report that demonstrates the association of carcinoma-specific complexes comprised of EpCAM with the variant isoforms of CD44 and claudin-7 in thyroid cancer including anaplastic thyroid cancer." (PMID 24727741, 2014). "An inverse association was observed between the expression of CD44s and EpCAM in the thyroid cancer cell lines examined in this study." (PMID 24727741, 2014). "In the differentiated thyroid cancers, membranous or cytoplasmic expression of EpCAM was detected in 37 of 38 cases, and nuclear expression of EpCAM was detected in only one case (2.6%)." (PMID 24727741, 2014). "The active form of EpCAM is known to localize to the nucleus, and therefore, localization of EpCAM was evaluated in 38 differentiated thyroid cancers and 37 anaplastic thyroid cancers." (PMID 24727741, 2014). "In the anaplastic cancer cell lines, most of the cells showed lower levels of CD44s, but higher expression of EpCAM than the two differentiated thyroid cancer cell lines." (PMID 24727741, 2014). "Although we analyzed only CD44v6 among the carcinoma-associated variants of CD44, our data suggested the interaction between EpCAM and the other carcinoma-associated variants of CD44 in thyroid cancer as well." (PMID 24727741, 2014). "In clinical specimens of thyroid cancers, nuclear expression of EpCAM and high expression of CD44v6 were detected significantly more frequently in anaplastic carcinomas." (PMID 24727741, 2014). "Double immunofluorescent staining of EpCAM and CD44s was conducted to detect the cells expressing these molecules in the four thyroid cancer cell lines." (PMID 24727741, 2014). "The nuclear expression of EpCAM was significantly more frequent in the anaplastic thyroid cancers compared to the differentiated thyroid cancers." (PMID 24727741, 2014).
thyroid cancer (continued). "A recent study examined the biological effects of EpCAM expression in thyroid cancer cells as a potentially important event in tumorigenesis." (PMID 23049733, 2012). "Nuclear accumulation of the intracellular domain of epithelial cell adhesion molecule (Ep-ICD) in tumor cells was demonstrated to predict poor prognosis in thyroid carcinoma patients in our earlier study." (PMID 23049733, 2012). "This may suggest a possible involvement of EpCAM in the progression from an indolent to an aggressive phenotype in thyroid carcinoma." (PMID 40965626, 2025). "The involvement of EpCAM, CD44v6 and claudin-7 in the thyroid cancer progression has been showed." (PMID 32091301, 2020). "Thus, the involvement of EpCAM in progression of thyroid cancer from an indolent to an aggressive phenotype has been suggested." (PMID 24727741, 2014). "Recent studies have demonstrated that nuclear localization of EpCAM could be a useful biomarker for aggressive thyroid cancer." (PMID 24727741, 2014). "We previously demonstrated that nuclear and cytoplasmic accumulation of the intracellular domain (Ep-ICD) of epithelial cell adhesion molecule (EpCAM) accompanied by a reciprocal reduction of its extracellular domain (EpEx), occurs in aggressive thyroid cancers." (PMID 21152431, 2010). "EpCAM is known to interact with claudin-7 and CD44v6 and plays an important role in tumor progression, and therefore, we tested whether both EpCAM and claudin-7 were expressed in the thyroid cancer cell lines." (PMID 24727741, 2014). "A positive correlation was observed between EpCAM expression and ALDH1 activity in thyroid cancer cell lines." (PMID 24727741, 2014). "Because higher EpCAM expression was observed in FRO and ACT-1 in vitro analyses, the expression of EpCAM was examined by immunohistochemistry in clinical thyroid cancer specimens." (PMID 24727741, 2014). "Finally, another study used three epithelial tumour markers known to be overexpressed in thyroid cancer: B7H3/CD276, MUC1, and EpCAM." (PMID 41193833, 2025). "On the contrary, in the differentiated thyroid cancer cell lines, which were mostly negative for EpCAM, the expression of ALDH1 was rarely detected." (PMID 24727741, 2014). "In addition, double immunofluorescent staining of EpCAM and CD44s demonstrated that EpCAM was not expressed in the cells strongly positive for CD44s, but was expressed in the cells weakly positive or negative for CD44s in the thyroid cancer cell lines." (PMID 24727741, 2014). "From a screen of eight thyroid cancer cell lines, we recently reported that there was no common thyroid CSC marker among 11 candidate markers [CD13, 15 (stage-specific embryonic antigen 1, SSEA-1), 24, 44, 44v, 90, 117, 133, 166, and 326 (epithelial cell adhesion molecule, EpCAM), and ALDH]." (PMID 26973599, 2016).